GPR35 (G protein-coupled receptor 35)
Description:
G protein-coupled receptor that binds to several ligands including the tryptophan metabolite kynurenic acid (KYNA), lysophosphatidic acid (LPA) or 5-hydroxyindoleacetic acid (5-HIAA) with high affinity, leading to rapid and transient activation of numerous intracellular signaling pathways. Ligand binding causes a conformation change that triggers signaling via guanine nucleotide-binding proteins (G proteins) and modulates the activity of downstream effectors, such as adenylate cyclase. GPR35 can couple with G(i)/G(o)- or G(12)/G(13) classes of G alpha proteins depending on the context, mediating the inhibition of adenylate cyclase or activation Rho small GTPases, respectively. KYNA-binding promotes monocyte adhesion to vascular endothelium under flow conditions, leading to G(i)/GNAI1 activation and inhibition of adenylate cyclase. Involved in cardioprotection during ischemia by promoting mitochondrial remodeling: following KYNA-binding and G(i)/GNAI1 activation, GPR35 is internalized to the outer mitochondrial membrane, where it inhibits mitochondrial adenylate cyclase (ADCY10), allowing ATPIF1 to repress ATP synthase activity. Stimulates lipid metabolism, thermogenic and anti-inflammatory gene expression in adipose tissue once activated by KYNA (By similarity). Plays a role in neutrophil recruitment to sites of inflammation and bacterial clearance through the major serotonin metabolite 5-HIAA that acts as a physiological ligand. In macrophages, activation by lysophosphatidic acid promotes GPR35-induced signaling with a distinct transcriptional profile characterized by TNF production associated with ERK and NF-kappa-B activation (By similarity). In turn, induces chemotaxis of macrophages (By similarity).
Tractability: Small molecule: a structure with a bound ligand is known; a high-quality ligand is known; it belongs to a druggable protein family. Antibody: UniProt places it where antibodies can reach, with high confidence; its Gene Ontology location is reachable by antibodies, with high confidence; UniProt predicts a signal peptide or a membrane-spanning region. PROTAC: a small molecule that binds it is known.
Target class: Membrane receptor; Family A G protein-coupled receptor; Small molecule receptor (family A GPCR); Kynurenic acid receptor; Carboxylic acid receptor
Chemical probes: CID 2745687 (high quality), ML 145 (high quality), ML144, PAMOIC ACID (high quality), PSB-13253 (high quality)
Gene: Protein-coding gene on chromosome 2 (240,605,430 to 240,633,159, forward strand). Ensembl gene ENSG00000178623.
Subcellular location: Cell membrane; Mitochondrion outer membrane
Pathways (Reactome):
Signal Transduction: Class A/1 (Rhodopsin-like receptors)
Gene Ontology:
Molecular function: C-X-C chemokine receptor activity; chemokine receptor activity; G protein-coupled receptor activity
Biological process: adenylate cyclase-inhibiting G protein-coupled receptor signaling pathway; chemokine-mediated signaling pathway; G protein-coupled receptor signaling pathway; leukocyte adhesion to vascular endothelial cell; monocyte chemotaxis; negative regulation of cardiac muscle cell apoptotic process; negative regulation of voltage-gated calcium channel activity; neutrophil chemotaxis; positive regulation of cytosolic calcium ion concentration; response to ischemia; cytoskeleton organization
Cellular component: mitochondrial outer membrane; plasma membrane; membrane
Genetic constraint (gnomAD): Loss-of-function variants: 1 observed, 1 expected, observed/expected ratio (o/e) 1, 90% interval 0.26 to 1.89. That is too few expected variants to judge how well the gene tolerates losing a copy. Missense variants: 372 observed, 420.96 expected, observed/expected ratio (o/e) 0.88, 90% interval 0.81 to 0.96. Synonymous variants: 207 observed, 194.68 expected, observed/expected ratio (o/e) 1.06, 90% interval 0.95 to 1.19.
Homologues: Orthologues: chimpanzee GPR35 (98% identical), macaque GPR35 (94% identical), mouse Gpr35 (72% identical), rat Gpr35 (72% identical), pig GPR35 (70% identical), dog GPR35 (68% identical), guinea pig GPR35 (63% identical), zebrafish gpr35.1 (30% identical). Paralogues in human: GPR55 (33% identical), LPAR4 (30% identical), LPAR6 (28% identical), GPR17 (27% identical), P2RY10 (26% identical), GPR4 (26% identical), GPR20 (25% identical), CYSLTR1 (24% identical), F2RL3 (24% identical), GPR18 (24% identical), P2RY8 (24% identical), CYSLTR2 (23% identical), and 4 more.
Diseases named in the same sentence as GPR35 in open-access papers:
GPR35 is named in the same sentence as 88 diseases in open-access papers, as found by Europe PMC text mining. Sharing a sentence is not in itself a finding about the gene and the disease. The quoted sentences say what the papers report.
colitis (23 papers, 2019 to 2026). Inflammation of the colon. "For instance, Macrophage-specific GPR35 deletion attenuates colitis-associated and spontaneous colon tumor formation by disrupting Na+/K+-ATPase (NKA)/Src-mediated angiogenesis and extracellular matrix remodeling." (PMID 41459506, 2025). "In DSS-induced colitis mouse models, the specific deletion of GPR35 in macrophages resulted in elevated inflammation associated with a decrease in TNF production in macrophages." (PMID 38035084, 2023). "GPR35 deficiency aggravated dextran sulfate sodium (DSS)‐induced colitis and led to neutrophil recruitment, as well as significantly decreased efficiency in clearing the number of peritoneal bacteria." (PMID 37423235, 2023). "We aim to understand the role of the GPR35 pathway in the tumour microenvironment of spontaneous and colitis-associated colon cancers." (PMID 33758004, 2022). "In subsequent studies, including ours, GPR35-deficiency led to exacerbated DSS colitis in mice as measured by clinical signs such as weight loss." (PMID 34790192, 2021). "GPR35 is highly expressed in immune and intestinal epithelial cells, and its loss of function has been shown to promote colitis in an experimental animal model." (PMID 33308304, 2020). "Therefore, as opposed to the Citrobacter rodentium infection model, epithelial GPR35 deficiency led to protection from BFT-induced colitis." (PMID 34790192, 2021). "Furthermore, loss of GPR35 in knockout mice aggravated the intestinal inflammation in DSS-induced experimental colitis." (PMID 31091682, 2019). "Collectively, our study demonstrates that the natural polyphenolic compound EA promotes epithelial healing and ameliorates colitis by acting as a GPR35 agonist." (PMID 41897369, 2026). "GPR35 protects the intestinal epithelium against experimental colitis induced by dextran sodium sulphate." (PMID 40121360, 2025). "GPR35 deficiency leads to impaired TNF synthesis and reduced corticosterone levels, thereby aggravating colitis severity." (PMID 41459506, 2025). "In this study, a DSS‐induced rat colitis model was established and 16S rRNA sequencing was applied to explore the influence of GPR35‐mediated KA sensing on gut microbiota homeostasis." (PMID 37423235, 2023). "Meanwhile, inhibiting the activation of colon GPR35 markedly blocked the effects of KA on colitis progression." (PMID 37423235, 2023). "GPR35 demonstrated a protective role in IBD as colitis worsened when GPR35 was genetically knocked out." (PMID 37834122, 2023). "Altogether, these results revealed decreased overall mortality, and decreased colitis-induced weight loss, and suggest that GPR35 contributes, at least, in part to early ETBF-induced colon inflammation." (PMID 33990686, 2021). "We next evaluated the contribution of GPR35 to the pathogenesis of ETBF in vivo using two mouse colitis models pretreated with antibiotics." (PMID 33990686, 2021). "Single nucleotide polymorphisms (SNPs) in GPR35 are associated with higher risk for IBD and loss of GPR35 aggravates disease in a DSS-induced colitis model." (PMID 34959809, 2021). "Activation by 6′SL and LNT of GPR35, a receptor mediating attenuation of pain and colitis, is to our knowledge the first demonstration of GPCR activation by any HMO." (PMID 32999316, 2020). "Kynurenic acid, a colitis-associated endogenous regulator, induces autophagy-dependent degradation of NLRP3 in macrophages via the kynurenic acid/G-protein-coupled receptor 35 (GPR35) axis." (PMID 40842999, 2025). "GPR35 agonism generally has beneficial effects on these tissues, including protective roles against cardiac ischemia, anti-nociception, anti-inflammatory roles in models of colitis, and prevention and reversal of lipid accumulation." (PMID 40978132, 2025). "Recent studies support GPR35’s therapeutic potential in colitis." (PMID 41459506, 2025).
colitis (continued). "There is considerable interest in assessing GPR35 as a therapeutic target in inflammatory bowel diseases because in Dextran Sodium Sulphate (DSS)-induced mouse models of colitis, activation of GPR35 is generally beneficial, although such conclusions are not universal." (PMID 39615676, 2024). "Therefore, in the present study, we established a DSS‐induced rat colitis model and a GPR35‐specific inhibitor (CID) was used." (PMID 37423235, 2023). "Besides, five classes and six genera were identified as the marked bacterial taxa that characterized the progression and outcome of colitis and are regulated by KA and its sensor GPR35." (PMID 37423235, 2023). "Therefore, the current study utilized the DSS‐induced rat colitis model to assess the influence of GPR35‐mediated KA sensing on gut microbiota homeostasis following KA administration and inhibition of the host GPR35 activity." (PMID 37423235, 2023). "In fact, GPR35 demonstrates protective qualities in scenarios such as DSS-induced colitis." (PMID 38035084, 2023). "Additional results demonstrated that inhibition of the host GPR35 activity dramatically blocked the ameliorative effect of KA on the taxa suggested that GPR35‐mediated KA sensing was closely related to the homeostasis of the 5 classes during the progression of colitis." (PMID 37423235, 2023). "Because GPR35 is also found on some immune cells, it is possible that not only GPR35 on CECs is important for BFT-induced colitis, but GPR35 may also be involved in the interplay between the immune system and CECs following ETBF colonization." (PMID 33990686, 2021). "Furthermore, several lines of evidence from multiple studies have shown that GPR35 is protective in dextran sodium sulfate (DSS) induced colitis mouse model." (PMID 34790192, 2021). "Interestingly, in the DSS colitis model, macrophage-specific GPR35 deletion led to elevated inflammation which was accompanied by reduced TNF responses in macrophages as well as intestinal corticosterone production." (PMID 34790192, 2021). "GPR35 is a receptor that mediates pain and colitis attenuation." (PMID 34859034, 2021). "However, CEC shedding in severe ETBF colitis in GPR35+/+ mice exceeded that observed in ETBF-colonized GPR35−/− mice." (PMID 33990686, 2021). "Together these data suggest that GPR35 may play a role in attenuating colitis, and that this effect could be due to its role in promoting wound healing and in attenuating inflammation." (PMID 32999316, 2020). "Additionally, the activation of GPR35 by pamoic acid significantly reduced the severity of DSS-induced colitis." (PMID 31091682, 2019). "Lack of GPR35 reduces tumour numbers in mouse models of spontaneous and colitis associated cancer." (PMID 33758004, 2022). "Importantly, GPR35 is required for the rapid onset of ETBF-induced colitis in mouse models." (PMID 33990686, 2021). "GPR35‐mediated KA sensing plays a crucial role in maintaining gut microbiota homeostasis, which contributes to alleviation of DSS‐induced colitis." (PMID 37423235, 2023). "These in vivo results add to our in vitro results indicating that GPR35 mediates, in part, the early signaling response to BFT, and has an early impact on ETBF colitis." (PMID 33990686, 2021). "Herein, given our in vitro results on the early contribution of GPR35 in BFT signaling, we focused on the evaluation of the early phase of ETBF colitis." (PMID 33990686, 2021). "Furthermore, we provide compelling evidence suggesting that GPR35‐mediated KA sensing plays a crucial role in maintaining gut microbiota homeostasis, which contributes to alleviation of DSS‐induced colitis." (PMID 37423235, 2023). "Despite the reduced goblet cell numbers and Muc2 expression in the proximal colon and increased Mucispirillum Schaedleri abundance in mice lacking epithelial Gpr35, we did not observe any signs of spontaneous colitis in these animals." (PMID 35264769, 2022).
colitis (continued). "Following the occurrence of colitis (Day 10), there was an observed increase in the phosphorylation of ERK1/2 within colon tissue, indicating activation of GPR35, which may be attributed to the increase of Trp-KYN-KA axis metabolism following the intestinal damage." (PMID 41513630, 2026). "The reduced incidence and size of tumours in Gpr35ΔMΦ mice was not linked to protection from DSS-induced colitis, as weight loss during short-term (ie, 7 days) DSS, nor during the three cycles of AOM/DSS was indifferent between Gpr35+/+ and Gpr35–/–, and Gpr35fl/fl and Gpr35ΔMΦ mice." (PMID 33758004, 2022). "First, in an experiment with severe colitis in clin/strep pretreated mice, ETBF colonization resulted in the death of 5/6 wild-type (GPR35+/+) mice, while none of the GPR35−/− mice died in the same experiment after ETBF colonization (n = 6 each, P = 0.0186, log-rank test)." (PMID 33990686, 2021).
inflammatory bowel disease (18 papers, 2015 to 2025). A spectrum of small and large bowel inflammatory diseases of unknown etiology. "The GPR35-T108M risk variant, which increases risk for primary sclerosing cholangitis and inflammatory bowel disease, leads to lower intracellular Na+ levels, and enhanced glutamine uptake." (PMID 40121360, 2025). "There are multiple single nucleotide polymorphisms (SNPs) located within the GPR35 gene linked with various immune and inflammation-related diseases, such as inflammatory bowel diseases, ankylosing spondylitis, and primary sclerosing cholangitis." (PMID 38035084, 2023). "The strong link between sequence variants of GPR35 and various inflammatory diseases of the lower gut has focused attention on inflammatory bowel diseases, but a wide range of other areas are also being considered." (PMID 35101446, 2022). "The inadequate GPR35 signaling is closely associated with an increased risk of inflammatory bowel diseases (IBDs), both ulcerative colitis and Crohn’s diseases, as well as primary sclerosing cholangitis." (PMID 36543774, 2022). "The orphan receptor G protein–coupled receptor 35 (GPR35) has been associated with a range of diseases, including cancer, inflammatory bowel disease, diabetes, hypertension, and heart failure." (PMID 29860395, 2018). "In the past, genome-wide association studies have associated GPR35 with diseases such as inflammatory bowel disease, type 2 diabetes, and coronary artery disease." (PMID 25805994, 2015). "The T108M polymorphism in GPR35 confers risk for inflammatory bowel disease and PSC." (PMID 40121360, 2025). "Genome‐wide association studies have identified GPR35 single nucleotide polymorphisms as a risk factor for inflammatory bowel disease (IBD), suggesting that GPR35 plays an important role in intestinal homeostasis." (PMID 37423235, 2023). "One exception to that is the identification of a single nucleotide polymorphism in GPCR GPR35 (rs4676410) among patients with inflammatory bowel disease (IBD)." (PMID 35883686, 2022). "GPR35 controls lipid metabolism and stimulates thermogenic programs in adipocytes as well as immune cell recruitment in different situations, while its function in the intestine is associated with inflammatory bowel disease, bacterial infection, and oncogenic signaling." (PMID 35933013, 2022). "Keywords included ‘inflammatory bowel disease’, ‘colorectal cancer’, ‘AhR’, ‘aryl hydrocarbon receptor’, ‘GPR35’, ‘cytochrome P450’, ‘nutraceuticals’, ‘probiotics’, and ‘superfoods’." (PMID 41009721, 2025). "Gpr35 has been suggested as a potential risk factor associated with chronic inflammatory conditions of the gastrointestinal tract, such as inflammatory bowel disease (IBD) and ulcerative colitis." (PMID 38229193, 2024). "Aminosalicylates, a first-line treatment for inflammatory bowel diseases (IBDs), have shown activity on both human and mouse GPR35, although their exact target remains undefined." (PMID 38035084, 2023). "Within the intestine, the human G protein–coupled receptor (GPCR) GPR35 is involved in oncogenic signaling, bacterial infections, and inflammatory bowel disease." (PMID 35933013, 2022). "Orphan receptor GPR35, which is predominantly expressed in the gastrointestinal tract and is closely related to inflammatory bowel diseases (IBDs), stands out as a prototypical receptor for investigating ionic modulation and G13 coupling." (PMID 36543774, 2022). "Recent literature has begun to highlight a potential role for GPR35 in a number of disease pathologies including hypertension and heart failure, asthma, pain, inflammatory bowel disease and both ulcerative colitis and primary sclerosing cholangitis." (PMID 27064272, 2015). "Intriguing examples such as GPR35 for inflammatory bowel disease and CXCR4 for viral infection are used as illustrations of how a systematic approach can aid in the prioritization of interesting drug discovery hypotheses." (PMID 30285606, 2018).
inflammatory bowel disease (continued). "This review synthesizes current evidence on the interplay between the aryl hydrocarbon receptor (AhR), G protein-coupled receptor 35 (GPR35), cytochrome P450 enzymes, and dietary ligands in the context of inflammatory bowel disease (IBD) and colorectal cancer (CRC)." (PMID 41009721, 2025).